BDNF (brain derived neurotrophic factor)
Diseases named in the same sentence as BDNF in open-access papers (continued):
Sharing a sentence is not in itself a finding about the gene and the disease.
depression (continued). "If trim‐and‐fill estimation reveals numerous missing reports, suggesting publication bias, it would be unreliable to accept research that states that peripheral levels of BDNF are decreased in depression." (PMID 35510613, 2022). "Both disturbances of the BDNF–TrkB pathway and abnormalities in cortico-striatal circuits are characteristic of depression." (PMID 36430271, 2022). "Recent studies showed that PAE reshaped the cocaine- and amphetamine-regulated transcript peptide and the brain-derived neurotrophic factor of the brain, both of which also participated in the development of depression in offspring." (PMID 35685596, 2022). "Increased BDNF signaling in the VTA-NAc mesolimbic pathway promotes a depression-like phenotype, whereas viral-mediated local knockdown of BDNF in the VTA has the opposite effect." (PMID 36088447, 2022). "The year-on-year increase in the number of publications reflects, to some extent, the growing scientific attention on depression and BDNF." (PMID 36291673, 2022). "Animal studies show both BDNF and NGF to be active in various experimental models of depression, wherein BDNF is active even with a single administration, while a chronic administration is required for the manifestation of the NGF antidepressant-like effect." (PMID 35337082, 2022). "Targeting the BDNF-TrkB (tropomyosin receptor kinase B) signaling pathway is a promising strategy to develop novel drugs for the treatment of depression." (PMID 35626632, 2022). "In a word, NAOs effectively reversed the CRS-induced mice model of depression, which depended on the changes in the gut microbiota and SCFAs, as well as its modulation of 5-HT and BDNF." (PMID 36422003, 2022). "Changes in BDNF levels in the central nervous system disrupt the entire signaling pathway, which can lead to various psychological disorders, including depression." (PMID 36014336, 2022). "A genetic research found that genetic variations in the p11/tPA/BDNF pathway play a central role with post-stroke depression." (PMID 35222248, 2022). "The relationship of BDNF with obesity and depression has been the subject of many investigations which collectively described a reduction of brain BDNF levels in both obesity and depression." (PMID 35911513, 2022). "FM as a heterogenic condition having both prominent pain and depression seems unpredictable to BDNF level measurements regarding different situations and treatments." (PMID 35501732, 2022). "A meta-analysis review has shown that low BDNF is a promising marker for the presence of depression and response to treatment." (PMID 36075922, 2022). "Diminished BDNF production exposes to a great depression vulnerability; however, physical exercise is considered one of the tools able to improve BDNF balance, stress, and sleep." (PMID 36035468, 2022). "Platelet serotonin levels do not differ between depressed and control subjects, whereas both reduced platelet BDNF content and plasma BDNF levels were found in subjects with depression." (PMID 35911513, 2022). "On the other hand, significant interactions have been observed between BDNF rs6265 and self-reports of childhood adversity in individuals with impaired hippocampal growth and depression." (PMID 35886019, 2022). "BDNF is a neurotrophic factor expressed in the hippocampus and is thought to play a key role in depression." (PMID 35436848, 2022). "GST therapy mediates antidepressant benefits through activation of the cyclic AMP response element-binding protein (CREB) and brain-derived neurotrophic factor (BDNF) signalling pathways in a chronic unpredictable stress model of depression in mice." (PMID 35164154, 2022). "In patients with depression, elevated blood cortisol and reduced BDNF expression were accompanied by HPA axis abnormalities." (PMID 36614066, 2022).
depression (continued). "Another TAAR1 and TAAR5 ligand T1AM increased ERK levels and adult neurogenesis in the hippocampus, while ERK MAP-kinase is the key molecule of BDNF signaling and mediates antidepressant efficacy in humans and animal models of depression." (PMID 35681508, 2022). "IL4‐driven microglia, characterized by high expression of Arg1, in the hippocampus trigger BDNF‐dependent neurogenesis, which is a response to chronic stress and a protection against depression‐like behaviors." (PMID 34878231, 2022). "Quercetin combined with exercise therapy can increase the expression of BDNF protein in 1,2-dimethylhydrazine-induced depression model rats with colorectal cancer and can act on the TrKβ/β-chain protein axis to treat depression." (PMID 36408279, 2022). "Three reports studied the effect of unpredictable chronic mild stress (a model of stress-induced depression) on the gut microbiota and neurogenesis or BDNF." (PMID 36555576, 2022). "Brain-derived neurotrophic factor (BDNF) is an important mediator involved in the regulation of normal brain development and neuroplasticity, and indeed BDNF abnormalities in signaling pathways play an important role in the development of depression." (PMID 36297314, 2022). "Noradrenaline also has impact on neuroplasticity via brain-derived neurotrophic factor, which is key for prefrontal and hippocampus neurons playing a role in depression." (PMID 36590208, 2022). "Signaling via BDNF and its receptor tropomyosin receptor kinase B (TrkB) plays a vital role in the etiopathogenesis of depression and the therapeutic mechanism of antidepressants." (PMID 36499295, 2022). "A recent study claimed that the hydroalcoholic extract of Cinnamomum (HEC) ameliorated depression symptoms in rats through the upregulation of the BDNF protein and its TrkB receptor in the prefrontal cortex." (PMID 36499295, 2022). "RAS performs an integral effect in mediating BDNF, which is essential in the neurobiology of depression and antidepressant effects." (PMID 36761172, 2022). "Depressed individuals have decreased levels of BDNF in the blood and brain structures connected with depression, such as the hippocampus." (PMID 35955633, 2022). "BDNF is involved in not only depression but also a lot of other neurological disorders such as Alzheimer’s disease, Parkinson’s disease and stroke." (PMID 35959431, 2022). "Oxidative stress eventually leads to the depression of animals after stress, and the symptoms of depression were significantly improved after using drugs that can increase the level of BDNF or show antioxidant effect in animals." (PMID 35663199, 2022). "Regarding BDNF measured in blood, evidence shows that serum/plasma BDNF levels increase in response to antidepressant treatment in patients with major depressive disorder." (PMID 35250657, 2022). "Multiple lines of evidence suggest that the BDNF-TrkB signaling pathway plays a role in the pathophysiology of depression and the therapeutic mechanisms of antidepressants." (PMID 36316319, 2022). "Clinical studies have confirmed that BDNF levels in plasma are decreased in case of depression, and antidepressant treatment can increase BDNF levels." (PMID 35873590, 2022). "Substantial evidence also demonstrated that people with depression or anxiety have decreased levels of BDNF, a marker of neuronal growth and plasticity." (PMID 35678014, 2022). "The expression of BDNF mRNA and protein have also been investigated in humans with depression and antidepressant treatment." (PMID 36407765, 2022). "In a mouse model of depression, melatonin displays antidepression effects with the elevation of BDNF levels in the hippocampus." (PMID 36699021, 2022). "The link between changes in neuroplasticity and depression has recently gained a lot of attention and it has been reported in many studies that BDNF level are strongly affected in depression." (PMID 36217471, 2022).
depression (continued). "SIRT1 participates in depression through various mechanisms, covering inflammation, BDNF signal, and neuronal excitability." (PMID 35664490, 2022). "Citalopram’s influence typically unfolds as the ability to reverse stress-induced BDNF decreases in rodent models of depression based on stress exposure." (PMID 36430520, 2022). "Our data suggest that (R)-ketamine shows prophylactic effects on LPS-induced depression-like phenotype via BDNF-TrkB signaling." (PMID 35064103, 2022). "We also found a significant association between plasma BNDF levels and frailty, even after excluding participants with BDNF-related metabolic and neuropsychiatric disorders, such as dementia, depression, diabetes, CVD, stroke, and osteoporosis." (PMID 36329115, 2022). "Nox1-induced ROS in the prefrontal cortex downregulated the level of BDNF, promoting depression in mice." (PMID 35850611, 2022). "Chronic stress and depression are known to impair BDNF synthesis in the hippocampus and cerebral cortex." (PMID 35939172, 2022). "This is consistent with the restoration of lost spines that occurs in depression models after successful antidepressant therapy, and relies on the normalization of BDNF and cortisol levels." (PMID 35733193, 2022). "BDNF plays important role in protecting against neurodegeneration and promoting neuronal plasticity, thereby having potential in depression treatment." (PMID 36117650, 2022). "Clinical studies have shown that patients with severe depression have a low level of BDNF in the hippocampus and prefrontal cortex, accompanied by cerebral hippocampus atrophy, neuronal apoptosis and synaptic loss." (PMID 36158555, 2022). "A decrease in the nerve growth factor (NGF), as well as BDNF level, was found in the blood plasma of people suffering from depression and also in the hippocampus of suicide victims." (PMID 35337082, 2022). "In mouse model of depression, epigenetic modifications result in alteration of chromatin structure of BDNF." (PMID 36583185, 2022). "BDNF levels increase after treatment (effect size 0.62, 95% CI 0.36–0.88), and this increase correlates with improvement in depression scores changes (p = 0.02)." (PMID 35546921, 2022). "It employs anti-depressant effects in a model of agitated depression via the inhibition of the kynurenine pathway, the downregulation of inflammatory cytokines, and elevation in the levels of serotonin (5HT) and BDNF." (PMID 35630774, 2022). "After the oral administration of 5-HTP, BDNF levels in the hippocampus were significantly recovered in the mice with depression-like behaviors." (PMID 35572711, 2022). "Treatments with gallic acid and P2X7 shRNA successfully increased the BDNF level in the hippocampus of comorbid rats, indicating alleviated depression." (PMID 35682841, 2022). "Using linear mixed model, we showed that duloxetine reduced BDNF level significantly in FM patients, even after adjusting for depression, pain and severity of the disease (P < 0.01)." (PMID 35501732, 2022). "In the pathogenesis of depression, the increased pro-inflammatory cytokines in the brain are known to impair neuronal functions by down-regulating the expression of BDNF." (PMID 35242039, 2022). "Based on accumulating evidence, the BDNF-TrkB signaling pathway plays a key role in the pathophysiology of depression and the therapeutic mechanisms of antidepressants." (PMID 36316319, 2022). "Pathologically, serum BDNF levels decrease in patients with Alzheimer’s disease, schizophrenia, and depression." (PMID 35998179, 2022). "One of the possible explanations for depression is the insufficient production of neurotrophic factors (e.g., brain-derived neurotrophic factor (BDNF)) in depressed individuals." (PMID 36422003, 2022). "Brain-derived neurotrophic factor (BDNF) signaling pathway is involved in the pathophysiology of depression and insomnia." (PMID 36498709, 2022).
depression (continued). "Abnormalities in BDNF are involved in the pathogenesis of several neuropsychiatric disorders, including anxiety and depression, as well as in stress-induced psychopathologies." (PMID 35344113, 2022). "Certainly, given the heterogeneous nature of the FM and depression, it seems hard to formulize the relation of the BDNF with pain and depression." (PMID 35501732, 2022). "As a result, in this current study, we explored the possible reason behind the conflicting outcome across studies of BDNF and depression by evaluating and/or comparing the BDNF concentrations in both drug‐naïve or drug‐free patients and healthy controls." (PMID 35510613, 2022). "The decrease in brain-derived neurotrophic factor (BDNF) and insulin-like growth factor (IFG-I) will increase the risk of depression." (PMID 36010610, 2022). "Taken together, our results indicated that inflammation-activated C/EBPβ mediated HFD-induced depression-like behaviors by downregulating BDNF and promoting AMPARs internalization." (PMID 36578534, 2022). "In the present work, the role of telomere length along with BDNF, as an intermediary between loneliness and depression, and its relationship with a worse state of health are discussed." (PMID 36497531, 2022). "In a learned helplessness rat model of depression, the levels of the BDNF pro-peptide were significantly higher in the medial prefrontal cortex (mPFC) of susceptible rats compared to controls, but levels were much lower in the nucleus accumbens (NAc)." (PMID 35887357, 2022). "A key role of brain-derived neurotrophic factor (BDNF) was recently demonstrated in the pathogenesis of major depressive disorders." (PMID 35159280, 2022). "The effect of zinc itself on depression has been broadly studied, and an interaction between zinc, BDNF and neuropeptides is emerging." (PMID 36430921, 2022). "A growing body of evidence suggests that BDNF is involved in depression, as its levels are significantly reduced in depressed individuals." (PMID 35850718, 2022). "Brain-derived neurotrophic factor (BDNF) has a critical role in stress response including neuropsychiatric disorders that are precipitated by stress, such as major depressive disorder (MDD)." (PMID 35722560, 2022). "It has neuroprotective effects and prevent the occurrence of depression by upregulating the expression of TrkB, BDNF, and mTOR, as well as by downregulating the activity of the HPA axis." (PMID 36506414, 2022). "Recent studies have found abnormal levels of brain-derived neurotrophic factor (BDNF) in a variety of central nervous system (CNS) diseases (e.g., stroke, depression, anxiety, Alzheimer’s disease, and Parkinson’s disease)." (PMID 35814950, 2022). "A meta‐analysis study of the peripheral manifestation of brain‐derived neurotrophic factor in relation to depression." (PMID 35510613, 2022). "Nagahara highlighted the therapeutic potential of BDNF in a range of CNS disorders, including depression." (PMID 36686689, 2022). "Chronic social defeat stress in a rat model of depression has revealed a significant reduction of BDNF levels in the hippocampus and prefrontal cortex." (PMID 35711916, 2022). "BDNF has been related to depressive symptoms, among others, because low levels of BDNF have been found in patients with major depression." (PMID 35886019, 2022). "Treatment with IAA for 5 weeks attenuated depression and anxiety-like behaviours, improved hypothalamus–pituitary–adrenal axis dysfunction and increased brain-derived neurotrophic factor expression." (PMID 36501051, 2022). "Some monoamine reuptake inhibitors applied in clinical practice have been found to increase the expression of BDNF in depression-like rodent models." (PMID 35712727, 2022). "Multiple studies have suggested that BDNF-TrkB signaling is important in the pathophysiology of depression and as a therapeutic target for antidepressants." (PMID 35291971, 2022).
depression (continued). "The optimization of BDNF levels helps synaptic plasticity and remodeling, improves neuronal damage, and relieves depression." (PMID 36408279, 2022). "The baseline BDNF level in patients suffering from depression was found to be lower compared to healthy subjects." (PMID 35546921, 2022). "In this study, a total of 5300 publications on the role of BDNF in depression and treatment were collected from the Web of Science core collection (WoSCC), which were published in 822 journals between 1999 and 2022." (PMID 36291673, 2022). "A review on DNA methylation in depression demonstrated a connection between depression and methylation of BDNF and NR3C1 genes, while the correlation of SLC6A4 with depression was conflicted." (PMID 35807931, 2022). "The present study aimed to analyze the effects of augmented MBCT combined with standard treatment (mainly pharmacotherapy) on depression patients about their psychological state, compliance, BDNF, and NGF expression levels." (PMID 35069013, 2022). "Depression is accompanied by a decrease in BDNF and a concomitant decrease in CREB, followed by behavioral changes and an increase in depressive states." (PMID 36430254, 2022). "The molecular mechanisms such as monoamine neurotransmitters, brain-derived neurotrophic factor, inflammatory factors, and glutamate that are similar in chronic pain and depression have also been discussed." (PMID 36171845, 2022). "Deletion of brain-derived neurotrophic factor (BDNF) and upregulation of indoleamine 2,3-dioxygenase 1 (IDO1) are associated with depression severity in animals." (PMID 35711916, 2022). "More recent studies have indicated that in the hippocampus EGCG provides relief from depression by downregulating IL-1β and upregulating BDNF in a mouse model." (PMID 36499295, 2022). "Numerous studies have shown that BDNF is involved in several psychiatric disorders, including depression and SCZ." (PMID 36552127, 2022). "An interesting clinical study has found that PD patients with higher self-rating Depression Scale (SDS) score show lower serum BDNF level." (PMID 36158555, 2022). "It exhibits a potent therapeutic action against depression by upregulating BDNF levels in the hippocampus." (PMID 36499295, 2022). "In stress models, BDNF mRNA and protein levels are decreased in the PFC and hippocampus whereas BDNF expression is increased in the amygdala, which is accompanied by depression-like and anxiety-like behaviors." (PMID 36076917, 2022). "Chronic CUR also resulted in a dose-dependent increase in hippocampal BDNF in a model of depression." (PMID 35216083, 2022). "The most important finding of this study is the different response observed after a stress challenge (TSST) in the levels of cortisol and BDNF in primary and induced depression." (PMID 35370811, 2022). "We propose that future research should consider all the factors affecting BDNF and assess the level of proBDNF and mBDNF separately while evaluating the patients with depression objectively." (PMID 35510613, 2022). "Previous research has found that peripheral BDNF levels were also reduced in patients with major depressive disorder and bipolar affective disorder who were acutely depressed." (PMID 35447946, 2022). "Further studies found that maternal deprivation increased HDAC2 expression in VTA dopaminergic neurons and increased BDNF (a biological indicator closely related to the onset of depression) expression in VTA." (PMID 35865627, 2022). "Experimental research reported that an acute dose of ketamine increases hippocampal BDNF expression in depressant-like adult rats induced by chronic postsurgical pain, mitigating depression-like features." (PMID 36355545, 2022). "Increased MMP-9 expression was considered to be as a compensatory response to reduction of mature BDNF in patients with major depressive disorder." (PMID 35370878, 2022).